LINC01352 (long independently transcribed non-coding RNA 1352)
Gene: Long non-coding RNA gene on chromosome 1 (220,829,255 to 220,832,429, forward strand). Ensembl gene ENSG00000238078.
Diseases named in the same sentence as LINC01352 in open-access papers:
LINC01352 is named in the same sentence as 3 diseases in open-access papers, as found by Europe PMC text mining. Sharing a sentence is not in itself a finding about the gene and the disease.
LINC01352 shares sentences with these, for which no sentence is quoted: cancer (1 paper); hepatocellular carcinoma (1); liver cancer (1).